KMT2D (lysine methyltransferase 2D)
Diseases named in the same sentence as KMT2D in open-access papers (continued):
Sharing a sentence is not in itself a finding about the gene and the disease.
follicular lymphoma (16 papers, 2020 to 2025). Follicular lymphoma is a form of non-Hodgkin lymphoma characterized by a proliferation of B cells whose nodular structure of follicular architecture is preserved. "In various B cell lymphomas, such as diffuse large B cell lymphoma (DLBCL) or follicular lymphoma (FL), somatic mutations in KMT2D (MLL2), EZH2, CREBBP, and TET2 are frequent events, affecting germinal center (GC) formation and affinity maturation." (PMID 37648814, 2023). "The gene encoding the lysine-specific histone methyltransferase KMT2D has emerged as one of the most frequently mutated genes in follicular lymphoma and DLBCL." (PMID 35646048, 2022). "In patients with follicular lymphoma (FL), we, as others, identified frequent mutations in KMT2D, CREBBP, and EZH2 with frequencies of 8/10, 5/10, and 4/10, respectively." (PMID 32013121, 2020). "KMT2D is frequently mutated in DLBCL (~ 30% of de novo cases, including both germinal center B-cell and activated B-cell subtypes and follicular lymphoma (~ 90%))." (PMID 38914869, 2024). "Overall, the mutation profile of the MYC/BCL2/BCL6-TH group is very similar to that of the MYC/BCL2-DH group, characterised by frequent mutations in follicular lymphoma associated genes (BCL2, CREBBP, KMT2D, EZH2, TNFRSF14)." (PMID 38184753, 2024). "KMT2D is considered a tumor suppressor gene, and its mutations are associated with non-Hodgkin lymphoma, including diffuse large B-cell (DLBCL) and follicular lymphoma, as well as some solid tumors such as small cell lung cancer." (PMID 39025450, 2024). "Of these, mutations in CREBBP, KMT2D, TNFRSF14 and RRAGC were enriched in follicular lymphoma, and those of BTG2, HLA-A, PIM1, IGLL5, SOCS1, CD83 and SGK1 were enriched in DLBCL." (PMID 33945543, 2021). "In addition, each contingent showed its own pathogenic variants, such as BCL2, KMT2D, EP300 in the follicular lymphoma contingent, and XPO1, TNFAIP3, and CREBBP in the cHL contingent." (PMID 36428786, 2022). "As expected, mutations in frequent drivers such as CREBBP, KMT2D,TNFRSF14 and RRAGC were more frequent among follicular lymphomas, those of MYC, CCND3 and ID3 prevailed among Burkitt lymphoma and those of BTG2, PIM1, SGK1 and SOCS1 were more frequent among DLBCL." (PMID 33945543, 2021). "Recurrent mutations of genes involved in epigenetic regulation (e.g. KMT2D, CREBBP, and EZH2), JAK-STAT pathway (e.g. SOCS1, STAT6), immune signaling (i.e. TNFRSF14), and BCR/NFKB signaling (e.g. CARD11, CD79B) were previously reported in follicular lymphoma cases." (PMID 35795062, 2022). "In acute myeloid leukemia, follicular lymphoma and DLBCL, KMT2D could inhibit tumorigenesis and metastasis, but in solid cancer, such as prostate cancer, KMT2D is critical factor for promoting tumor cell proliferation." (PMID 32695399, 2020).
Kabuki syndrome type 1 (16 papers, 2016 to 2025). "Kabuki syndrome type 1 (KS1) is a neurodevelopmental disorder caused by loss-of-function variants in KMT2D which encodes a H3K4 methyltransferase." (PMID 40971994, 2025). "Kabuki syndrome type 1 (KS1) is a Mendelian disorder of epigenetic machinery (MDEM) that results from pathogenic variants in KMT2D, a gene encoding a histone H3 lysine 4 (H3K4) methyltransferase." (PMID 37884963, 2023). "Here, we tested the hypothesis that KMT2D pathogenic loss-of-function variants, which causes the Kabuki syndrome type 1, could affect the mitochondrial metabolic profile." (PMID 32668765, 2020). "KMT2D activates transcription through trimethylation of the same amino acid, H3K4, and the disruption of its function is associated with Kabuki syndrome type 1 (OMIM:147920)." (PMID 39958159, 2025). "Kabuki syndrome type 1 (KS1) is an autosomal dominant, congenital, epigenetic disorder commonly associated with heterozygous loss-of-function variants in the lysine methyltransferase 2D gene, KMT2D (also known as MLL2/MLL4/ALR)." (PMID 38765012, 2024). "A potential postnatal treatment of Kabuki syndrome type 1 (KS1), caused by pathogenic variants in KMT2D encoding a histone-lysine methyltransferase, has emerged using a mouse model of KS1 (Kmt2d+/βGeo)." (PMID 37884963, 2023).
prostate carcinoma (16 papers, 2018 to 2025). A carcinoma that arises from epithelial cells of the prostate gland. "KMT2D has been reported to be highly mutated in prostate tumors, and high KMT2D transcription is associated with poor prostate cancer prognosis." (PMID 35715489, 2022). "A study showed that KMT2D was mutated in 8.6% of prostate cancer cases, while the genes of other MLLs had altered copy numbers or had mutations." (PMID 33302406, 2020). "Lysine methyltransferase 2D (KMT2D) has been established as a key oncogenic driver in prostate cancer, promoting tumor progression via multiple pathways." (PMID 41247636, 2025). "KMT2D has been studied extensively in prostate cancer and has also been shown to activate the PI3K/AKT pathway and support epithelial–mesenchymal transition pathways in carcinogenesis." (PMID 37566041, 2023). "Lysine (K)-specific methyltransferase 2D (KMT2D) is yet another epigenetic modifier that negatively regulates the expression of KLF4 in prostate cancer." (PMID 33266506, 2020). "WDR5 also binds to ACK1-mediated H4Y88ph and directs KMT2D to the promoter of the androgen receptor gene, thereby promoting its expression in castration-resistant prostate cancer." (PMID 33302406, 2020). "However, recent studies have also suggested that KMT2D greatly enhanced the proliferation, invasion, and tumor formation of gastric cancer or prostate cancer cells, implying that KMT2D acts on the tumor in either a promotive or a suppressive manner." (PMID 38015024, 2024). "Additional findings link KMT2D deletion in prostate cancer cells to increased sensitivity to both conventional chemotherapy and PARP inhibitors, making KMT2D expression status a potential novel biomarker for the prognosis of the treatment response." (PMID 37566041, 2023). "KMT2D, a histone methyltransferase that catalyzes the monomethylation of H3K4, has been shown to regulate the expression of antioxidant genes in prostate cancer." (PMID 36278682, 2022). "Taken together, our findings elucidate a critical KMT2D/G3BP1/SPOP/AR regulatory axis in prostate cancer progression and propose that targeted inhibition of histone methylation in combination with anti-androgen therapy represents a promising strategy for the management of advanced prostate cancer." (PMID 41247636, 2025).
gastric cancer (12 papers, 2013 to 2025). A primary or metastatic malignant neoplasm involving the stomach. "A previous genomics study showed that 47% of gastric cancer patients had mutations in KMT2C or KMT2D." (PMID 33726759, 2021). "For example, the dysregulation of enzymes like KMT2D (an HMT) and KDM2A (an HDM) is linked to various cancers including gastric cancer by influencing the chromatin structure and gene activity." (PMID 39765675, 2024). "The group with SOX2 suppression had higher rates of mutations in many gastric cancer-associated genes such as epigenetic modifiers ARID1A, KMT2D, KMT2C, and KMT2B, as well as higher rates of mutations in genes encoding for receptor tyrosine kinases ERBB4 and FGFR1." (PMID 40149431, 2025). "For example, PIK3CA mutation is associated with EBV-positive gastric adenocarcinoma, and KMT2D may promote the proliferation of gastric cancer cells." (PMID 39555091, 2024). "Similarly, studies using gastric cancer cell lines showed that KMT2D knockdown reduced phospho-AKT signals and cell proliferation." (PMID 34194626, 2021). "However, SOX2 suppression may be permissive for a sub-set of gastric cancers with CDX2 induction to acquire mutations in epigenetic modifier genes, including ARID1A, KMT2D, KMT2C, KMT2A, and KMT2B." (PMID 40149431, 2025).
melanoma (12 papers, 2018 to 2025). A malignant, usually aggressive tumor composed of atypical, neoplastic melanocytes. "For instance, in N-RAS-mutated melanoma, KMT2D activated enhancers for the cell migration-associated genes MFGE8 and RPL39L." (PMID 34194626, 2021). "Other study has shown that KMT2D deficiency sensitizes different types of syngeneic tumors (including lung tumor, bladder tumor, breast tumor, and melanoma) to anti-PD1, suggesting that anti-PD1 may have a stronger inhibitory effect on KMT2D-mutant tumors than on KMT2D-WT tumors." (PMID 34194626, 2021). "Recently, Kunal Rai1’s lab revealed that KMT2D was a tumor suppressor in melanoma based on an in vivo epigenome-focused pooled RNAi screen and confirmed the finding by using a genetically engineered mouse model." (PMID 37831226, 2023). "In melanoma cells, the histone methyltransferase KMT2D, which can methylate Lys-4 in histone 3, has been found to keep proximal and distal IGFBP5-regulating enhancers in an open state, thereby contributing to high IGFBP5 levels." (PMID 36093095, 2022). "One of the chromatin’s writer enzymes that has been identified to function aberrantly in melanomas is the KMT2D, also known as MLL2." (PMID 34575678, 2021). "The author could not find a report that describes this co-occurrence in clinical samples however a recent mouse study demonstrated that KMT2D functions as tumor suppressor in BRAF V600E mutant melanomas." (PMID 36275468, 2022). "Among them, KMT2D orchestrates a migratory transcriptional program in NRAS melanomas." (PMID 34575678, 2021). "Both KMT2D and IGFBP5 act as tumor suppressors in melanoma cells and, in metastatic melanoma, the IGFBP5 level correlates with that of KMT2D." (PMID 36093095, 2022).
pancreatic cancer (12 papers, 2018 to 2026). "Given that KMT2D executes its antitumor function via catalyzing the formation of H3K4me1 in pancreatic cancer, we explored the genes associated with H3K4me1." (PMID 38015024, 2024). "The gene named AURKB is known to suppress proliferation of pancreatic cancer, and KMT2D is also known to be associated with pancreatic cancer." (PMID 29697368, 2018). "In addition, KMT2D deficiency augments the tumor-inhibitory effect of the curcumin analog L48H37 on pancreatic cancer cells and increases the sensitivity of other cancer cells to chemotherapeutic drugs, such as doxorubicin, carboplatin, and the nucleotide analog Fluorouracil." (PMID 34194626, 2021). "The mechanisms regulating KMT2D expression and its downstream effects in pancreatic tumorigenesis represent a potential therapeutic approach to pancreatic cancer as an epigenome-regulated metabolic disease." (PMID 37394582, 2023). "Histone lysine (K)-specific methyltransferase 2D (KMT2D) inhibitor increased aerobic glycolysis and changed the liposome characteristics of pancreatic cancer cells." (PMID 33344447, 2020). "In the present review, we summarized the mutations of epigenetic regulators, including ARID1A, SMARCA2, SMARCA4, KDM6A, KMT2C, KMT2D, and BRD4 in GI cancers—in particular, pancreatic cancer—and found these regulators to be frequently mutated." (PMID 31238554, 2019). "KMT2D was transcriptionally repressed by DNA methylation in pancreatic tumors." (PMID 37394582, 2023). "High expression of KMT2D was related to poor survival outcomes of pancreatic cancer patients." (PMID 37370109, 2023). "Moreover, some research demonstrated that KMT2D is essential for tumor cell proliferation in many solid tumors, including pancreatic cancer, breast and colorectal cancer, and that KMT2D depletion increases the effectiveness of chemotherapy." (PMID 34758724, 2021). "KMT2D expression levels can be downregulated by DNA CpG methylation in pancreatic cancer cells." (PMID 34194626, 2021). "Based on the analysis, we surmise that KMT2D protein might exert tumor-promoting properties in pancreatic cancer." (PMID 34758724, 2021). "However, in vitro KMT2D depletion increases apoptosis and sensitivity toward 5-FU in pancreatic cancer." (PMID 31238554, 2019). "Therefore, KMT2D may play a new previously unknown anti-tumor effect by regulating glucose/fatty acid metabolism in pancreatic cancer." (PMID 33344447, 2020). "Inhibition of KMT2D promotes the metabolic transition to aerobic glycolysis by regulating glucose transporter 3 (SLC2A3), increasing the aerobic glycolysis rate and changing the lipid composition of pancreatic cancer cells." (PMID 37394582, 2023). "In addition, significant upregulation of a number of HMTs such as KMT5B, KMT2D (MLL2), NSD3 (nuclear SET domain-containing protein 3), PRDM16, MECOM (MDS1 and EVI1 complex locus protein) and NSD1 was observed in MCF7, MDA-MB-231, and pancreatic carcinoma PANC1 cell lines." (PMID 34884658, 2021).
B-cell lymphomas (11 papers, 2016 to 2025). "The reported co-occurring pattern of CREBBP and KMT2D mutations across B-cell lymphomas prompted us to further validate those findings in publicly available patient datasets." (PMID 38570506, 2024). "Loss of KMT2D in B cells in mice leads to the development of B-cell lymphomas, indicating that this gene is a bona fide tumor suppressor." (PMID 35237302, 2022). "Accordingly, loss-of-function mutations in KMT2D can occur in B-cell lymphomas together with GOF mutations of the EZH2 gene." (PMID 34202528, 2021). "CREBBP and KMT2D mutations frequently co-occur in B cell lymphomas with unclear significance." (PMID 38570506, 2024). "While KMT2C is identified as a tumor suppressor in acute myeloid leukemia (AML), the role of KMT2D remains unclear in this disease, though its loss promotes B cell lymphoma and various solid cancers." (PMID 37142882, 2023). "Thus, we identified here OAML as a further B cell lymphoma with highly recurrent KMT2D mutations and the first epigenetic regulator involved in the pathogenesis of OAML." (PMID 27566587, 2016). "Herein, we explored the puzzling co-occurrence of somatic mutations in the two enhancer activating chromatin modifier proteins CREBBP and KMT2D in B-cell lymphomas." (PMID 38570506, 2024). "While UTX mutations are rare in GC B-cell lymphomas, a high incidence of inactivating mutations in the components of COMPASS and its partner HATs, including KMT2D, CREBBP, and EP300, has been reported." (PMID 37198323, 2023). "Although KMT2D deficiency seems to sensitize tumors to ICB in solid cancers, this might not be the case for B cell lymphoma where concurrent mutations might alternatively lead to immune escape." (PMID 35237302, 2022).
developmental delay (11 papers, 2017 to 2025). "The current diagnosis relies mainly on the identification of infantile hypotonia, developmental delay, or intellectual disability, combined with typical dysmorphic features and KMT2D or KDM6A mutations based on genetic testing." (PMID 38115267, 2023). "It has been suggested that developmental delay is more pronounced in patients with KMT2D gene deletions or variants causing a dysfunction of synthesis in the first half of the KMT2D protein." (PMID 33805950, 2021). "Variants in both KMT2D and KDM6A lead to improper cell differentiation, ultimately causing a characteristic dysmorphism and developmental delay." (PMID 33805950, 2021).
Intellectual disability (11 papers, 2013 to 2023). "Pathogenic variants in KMT2D cause autosomal dominant Kabuki syndrome, a disorder characterized by distinctive facial features, intellectual disability, and abnormalities affecting other parts of the body." (PMID 34336928, 2021). "A deficiency in postnatal neurogenesis directly results in the KMT2D defect as the base for intellectual disability in KS." (PMID 33805950, 2021).
leukemia (11 papers, 2015 to 2025). A malignant (clonal) hematologic disorder, involving hematopoietic stem cells and characterized by the presence of primitive or atypical myeloid or lymphoid cells in the bone marrow and the blood. "CHEK2 is known to interact with several proteins that affect leukemia-specific pathways, such as KMT2D and FOXM1, but this remains to be explored further." (PMID 40335619, 2025). "Another leukemia study showed that KMT2D occupied and activated pro-tumorigenic HOXA9 target genes and that KMT2D was required for leukemogenesis mediated by co-expression of HOXA9 and MEIS1in vivo." (PMID 34194626, 2021). "Further, rapamycin‐treated leukemia cells were presented with smaller cell and nuclear sizes, pharmacologically reversing the effect of Kmt2d knockdown, further providing experimental evidence for the role of the mTOR signaling pathway played in the tumorigenesis." (PMID 37142882, 2023). "First, Kmt2d mRNA levels in harvested leukemia cells were dramatically reduced." (PMID 37142882, 2023). "We next determined the effect of SNDX-5613 on in vivo leukemia-initiating potential of primary PD AML cells harboring MLL-AF9 plus FLT-3 N676T, as well as mutations in KMT2C, KMT2D, NOTCH2, IRF8, ARID1A, VPS13A, and ABCA7, which were determined by whole-exome sequencing." (PMID 35017466, 2022). "This could indicate that discrepancies in the regulation of KMT2A and KMT2D in engrafted leukemia also affect specific target genes." (PMID 33722259, 2021). "We also found that the epigenetic regulator gene KMT2D, which is frequently mutated in ALL, may be involved in driving leukemia transformation, as evidenced by an in vitro functional assay." (PMID 32164600, 2020). "However, the function of KMT2D in leukemia pathogenesis remains uncharacterized." (PMID 32164600, 2020). "Then, since KMT2D is a writer of H3K4 mono‐ and di‐methylation, we also noticed the consistent reduction of H3K4me1 and H3K4me2 levels in leukemia cells with Kmt2d knockdown, indicating on‐target effects of shKmt2d." (PMID 37142882, 2023). "The protein level of KMT2A and KMT2D epigenetic regulators, and a few of their targets were found to fluctuate consistently between patients and their matched PDX leukemia." (PMID 33722259, 2021). "As KMT2D is a predicted tumor driver gene in ALL and it overexpressed in ALL, when KMT2D is knocked down, it significantly decreased leukemia cell growth, promoted cell apoptosis, and inhibited cell proliferation." (PMID 32164600, 2020). "Moreover, chromatin accessibility profiling of leukemia cells disrupted for cBAF (Smarcd2 knockout), MLL1 (Kmt2a knockout) or MLL4 (Kmt2d knockout) showed that these chromatin factors are required to maintain optimal accessibility at the Stat5a and Runx2 binding loci." (PMID 37580596, 2023). "Hence, the KMT2D gene plays an important role in hematological tumors and may act as a drug target in MLL-rearranged leukemia." (PMID 32164600, 2020). "In addition, KMT2D can interact with KMT2A in acute myeloid leukemia, its deletion reduced MLL-AF9 leukemia cell survival, and the codeletion of both KMT2A and KMT2D resulted in more severe reductions in survival, proliferation, and gene expression than either individual gene deletion." (PMID 32164600, 2020).